STAT1 (signal transducer and activator of transcription 1)
Diseases named in the same sentence as STAT1 in open-access papers (continued):
Sharing a sentence is not in itself a finding about the gene and the disease.
prostate carcinoma (continued). "Previous studies in prostate cancer demonstrated that STAT1 could enhance tumor progression through transcriptional regulation of LDHA and LDHB, highlighting its significant role in metabolic regulation 32, underscoring its role in metabolic regulation." (PMID 41208879, 2025). "Thus, in contrast to phospho-acetyl switch that inhibits STAT1 transcription activity upon its acetylation, AR seems to use both the modifications to allow prostate cancer to evolve through progressive stages to become CRPC." (PMID 35704598, 2022). "Notably, a similar mechanism appears manifest in prostate cancer cells that are vulnerable to MSC-derived IL-28 induced apoptosis via STAT1 activation." (PMID 33526787, 2021). "Since there is no change in the level of IL28Rα or IL10Rβ, it is not clear at this juncture what causes the termination of STAT1 phosphorylation in the MSC educated prostate cancer cells." (PMID 33526787, 2021). "More recently, STAT1 has emerged as a potential mediator of drug resistance in prostate cancer and may present a potential therapeutic target." (PMID 18492237, 2008). "In conclusion, CDKL3 was identified to possess a STAT1-dependent tumor-promoting factor in the development and progression of prostate cancer, which could contribute to the improvement of targeted therapy for prostate cancer." (PMID 36899018, 2023). "More importantly, the phenotypic changes of prostate cancer cells induced by CDKL3 were dependent on ERK pathway and STAT1." (PMID 36899018, 2023). "The overexpression of DTX3L promotes the phosphorylation of STAT1 and represses the transcription of IFN regulatory factor-1 (IRF-1), thus enhancing the proliferation, metastasis and chemoresistance of prostate cancer cells." (PMID 36614304, 2023). "Therefore, we can conclude that CDKL3 may promote the progression of prostate cancer through STAT1." (PMID 36899018, 2023). "The overexpression of DTX3L and BAL1 promotes the phosphorylation of STAT1 and represses the transcription of IFN regulatory factor-1 (IRF-1), thus enhancing the proliferation, metastasis, and chemoresistance of prostate cancer cells." (PMID 34513839, 2021). "In a study of patients with prostate cancer, 1,25(OH)D was found to suppress many JAK-STAT signal components, including JAK1, STAT1, STAT2 and STAT3, which is consistent with our study." (PMID 32158346, 2020). "In VCaP prostate cancer cells, treatment with T-474 or T-418 suppressed the phosphorylation of the known CDK8 substrate STAT1 at Ser727 both in the absence and in the presence of IFN-γ, which stimulates CDK8-mediated STAT1 phosphorylation." (PMID 29568371, 2018). "Thrombin inhibits cell growth by both up-regulation of STAT1 dependent p21waf/cip1 and induction of caspases via its PAR-1 receptor in DU145 prostate cancer cells." (PMID 26993600, 2016). "Inhibitory effects of silibinin on STAT-1, STAT-3, and STAT-5 phosphorylation were also observed in orthotopic xenograft of PC-3 human prostate carcinoma." (PMID 28030611, 2016). "However, a pro-metastatic role of IFNG has also been observed in prostate cancer cells, where it promotes EMT through the activation of Janus kinase/signal transducer and activator of transcription 1 signaling." (PMID 38287309, 2024). "Moreover, a potential downstream mediator, STAT1, was identified by a preliminary mechanistic study, whose essential role in CDKL3-induced prostate cancer regulation was subsequently proved." (PMID 36899018, 2023). "Knockdown of STAT1 could not only inhibit prostate cancer development in vitro, but also diminish the promotion effects induced by CDKL3 overexpression, highlighting the critical role of STAT1 as the mediator." (PMID 36899018, 2023).
prostate carcinoma (continued). "IFN-γ stimulating the IFNGR1 receptor complex induces the transcription factors including Signal Transducer and Activator of Transcription 1 (STAT1) and Interferon Regulatory Factor 1 (IRF1) to actuate the type II IFN response genes and chronic inflammatory reaction in prostate carcinoma cells." (PMID 35814468, 2022). "Meanwhile, a novel mechanism that IL-6 promoted prostate cancer metastases through a soluble IL-6 receptor (sIL-6R) without activation of STAT1, STAT3 or MAPK was also documented." (PMID 26528698, 2015). "Taken together, our findings identified a STAT1/lactate/NFκB1/MCP-1 positive feedback mechanism as a driver of prostate cancer progression and resistance to radiotherapy that functioned by interaction to macrophages, which could be potential therapeutic targets for the advanced prostate cancer." (PMID 41856970, 2026). "We also generated derivatives of 22Rv1 prostate cancer cells (which overexpress CDK19 relative to CDK8) with the knockout of CDK8 and CDK19, individually and in combination (dKO), and analyzed STAT1 S727 phosphorylation with and without IFNγ treatment." (PMID 37378433, 2023).
liver fibrosis (46 papers, 2010 to 2025). "CXCL10, interacting with its receptor CXCR3, activates the JAK/STAT1 pathway, contributing to macrophage polarization and CCl4-induced murine liver fibrosis." (PMID 41479922, 2025). "IFN-γ induces endothelial-mesenchymal transition by activating the JAK/STAT1 signaling pathway, thereby promoting hepatic fibrosis." (PMID 40421012, 2025). "Our study shows a significantly higher p-STAT3/p-STAT1 ratio in the liver fibrosis group, which further increases with anti-IFNAR blockade, suggesting STAT3’s role in mitigating fibrosis." (PMID 40260261, 2025). "In contrast, expression of the Signal transducer and activator of transcription 1 (Stat1) marker was downregulated in liver fibrosis." (PMID 38372748, 2024). "Rilpivirine represses liver fibrosis by selective STAT1-regulated apoptosis in hepatic stellate cells." (PMID 38431286, 2024). "Triggering IL6/STAT3 signaling enhances HSC activation and liver fibrosis, while IFNγ/STAT1 signaling exhibits opposite effects." (PMID 37860111, 2023). "It has been reported that the mice, struck off the STAT1 gene, are more likely to have chemically induced lung and liver fibrosis." (PMID 36915717, 2023). "It is well known that chronic alcohol use and LPS decrease ILs and IFN-induced STAT1 activation, which in turn lowers NK cell function in the liver and speeds up the development of hepatic fibrosis." (PMID 37446321, 2023). "We finally explored the effects of GZFL on TGF-β1/Smad2/3 signaling and IFN-γ/STAT1 signaling in CCl4-induced mouse model of liver fibrosis by using western blot." (PMID 35387552, 2022). "Evidences have shown that TGF-β1/Smad2/3 signaling play a pro-fibrotic role, while IFN-γ/STAT1/Smad7 signaling pathway exhibit an anti-fibrotic role in liver fibrosis progression." (PMID 35387552, 2022). "The key targets included 8 co-targets, including HSP90AA1, PPARG, HSP90AB1, STAT1, etc., which play pivotal roles in the pathogenesis of liver fibrosis." (PMID 33510287, 2021). "By mapping the candidate targets to the 66 known genes associated with hepatic fibrosis obtained from OMIM and DrugBank, 10 co-targets were found, including HSP90AA1, PPARG, MAPT, HSP90AB1, STAT1, and PPARA." (PMID 33510287, 2021). "Pparg and Stat1 play pivotal roles in the pathogenesis of liver fibrosis, but there is an upstream or downstream relationship between the two." (PMID 33510287, 2021). "Among them, STAT1 is a negative regulator of liver fibrosis, which can inhibit the activation and proliferation of HSCs and promote the killing ability of NK on activated HSCs40." (PMID 33510287, 2021). "Consistently, inhibition of the enhanced STAT1 signaling prevented T cell infiltration and liver fibrosis, suggesting a dual role of STAT1 in fibrotic development." (PMID 32708044, 2020). "The activation of STAT1 attenuates liver fibrosis through the inhibition of HSC proliferation, attenuation of TGFβ signaling, and stimulation of the NK cell killing of HSCs13." (PMID 28262670, 2017). "Collectively, these experiments highlighted the critical role of STAT1 in the progression of liver fibrosis and indicated that suppression of STAT1 promote the reversion of activated HSCs." (PMID 28322315, 2017). "Further investigation need to clarify the role of STAT1 or IFN signaling pathway in HSCs even more in liver fibrosis and recovery." (PMID 28322315, 2017). "Consistently, our study shows that the expression of STAT1 is higher in acute hepatitis and liver fibrosis phase but lower in normal and recovery phase." (PMID 28322315, 2017). "STAT1-/- mice shows decreased cytotoxicity of NK cell which negatively regulates S. japonicum egg-induced liver fibrosis." (PMID 28912762, 2017). "STAT1 is discussed to be a negative regulator in liver fibrosis and its activation was reported to inhibit signalling by TGF-β, one of the major players involved in liver fibrosis." (PMID 20719000, 2010).
liver fibrosis (continued). "Activation of STAT1 attenuates liver fibrosis through inhibition of HSC proliferation, attenuation of TGF-beta signaling, and stimulation of NK cell killing of activated HSCs." (PMID 20368974, 2010). "Besides that, FN induced a modest but statistically significant elevation in STAT1 phosphorylation, a negative regulator in hepatic fibrosis." (PMID 40852727, 2025). "For example, rilpivirine, an anti-HIV drug, has demonstrated significant antifibrotic and anti-inflammatory effects in liver fibrosis models by selectively activating the STAT1 pathway within the JAK-STAT signaling cascade, leading to hepatic stellate cell (HSC) apoptosis." (PMID 40449734, 2025). "STAT1 is another critical transcription factor implicated in diseases like recurrent aphthous stomatitis (RAS), inflammatory diseases, antitumor therapies, and liver fibrosis." (PMID 39844998, 2025). "Glycyrrhizic acid, an active metabolite derived from Glycyrrhiza uralensis Fisch (Gancao), can ameliorate liver fibrosis and inhibit hepatic stellate cell activation by enhancing the CUGBP1-mediated IFN-γ/STAT1/Smad7 pathways, indicating its potential as a preventive agent for liver fibrosis." (PMID 39301567, 2024). "Increasing evidence suggests that STAT1 could be a new therapeutic target for treating liver fibrosis." (PMID 39062027, 2024). "Another protein, signal transducer and activator of transcription 1 (Stat1) protein was upregulated (at 2.5-fold) with Aquamin® and it is considered an important negative regulator in liver fibrosis by inhibiting stellate cell proliferation through attenuation of TGF-beta signaling." (PMID 35634402, 2022). "Conversely, the expression levels of STAT1, a negative regulator of liver fibrosis, were reduced." (PMID 34699385, 2021). "Umbilical-cord-derived MSCs and also allogenic ABCB5-positive MSCs that improve liver fibrosis enhance regeneration, suppress inflammation, and downregulate Notch and Stat1/Stat3 signaling in rats are under clinical trials (NCT04822922, NCT03860155) for the treatment of patients with ACLF." (PMID 34820395, 2021). "For example, the dysregulated lncRNAs including NONMMUT014792.2, NONMMUT031907.2, NONMMUT061096.2, NONMMUT047510.2 and ENSMUST00000185516 may be co-expressed with TGFβ-1, JAK3, and STAT1, which are reported to be important regulators of liver fibrosis." (PMID 33261628, 2020). "Moreover, IFN-α reduced collagen expression and suppressed liver fibrosis though regulating STAT1 and p300." (PMID 32708044, 2020). "TGFβ1, STAT1, and CXCR46, 13, 25 have previously been implicated in liver fibrosis." (PMID 28262670, 2017). "STAT1 could be a new therapeutic target for treating alveolar echinococcosis, similar to that shown e.g. for liver fibrosis." (PMID 20368974, 2010). "The upregulation of STAT1 may be related to the effect of Rg1 in reducing liver fibrosis." (PMID 36077440, 2022). "In contrast, Col1A1, Timp1, and Tgfβ1 decreased, and Stat1 increased in both mRNA and protein levels following KIF18A overexpression in liver fibrosis models." (PMID 38372748, 2024). "The flavonoids enhanced the expression of Stat1, Pparg, Hsp90aa1 genes, signal transduction and transcriptional activator 1 (STAT1), and peroxisome proliferator-activated receptor G (PPARG) proteins, which play key roles in the pathogenesis of liver fibrosis." (PMID 37175164, 2023). "All these data suggested that GZFL was able to ameliorate liver fibrosis in vitro and in vivo by modulating the crosstalk between TGF-β1/Smad2/3 and IFN-γ/STAT1/Smad7 signaling pathway via CUGBP1." (PMID 35387552, 2022). "STAT3, a member of the same signaling pathway, has been shown to promote hepatic fibrosis, while STAT1 was found to counteract STAT3 and inhibit hepatic fibrosis." (PMID 36632136, 2022). "Rilpivirine, a widely used anti-HIV drug, has been shown to ameliorate liver fibrosis though suppressing STAT3 and promoting STAT1-mediated HSC apoptosis." (PMID 32708044, 2020).
liver fibrosis (continued). "IFN-γ induced Smad7 expression and impaired TGF-β signaling through activating STAT1 in activated HSCs, indicating anti-fibrotic roles of IFN-γ in liver fibrosis." (PMID 32708044, 2020). "GZFL could inhibit acetaldehyde‐induced cellular fibrosis and alleviate CCL4‐induced liver fibrosis by inhibiting TGF-β1/Smad2/3, CUGBP1 signaling and activating IFN-γ/STAT1/Smad7 signaling." (PMID 35387552, 2022). "Collectively, GZFL could reduce CCl4-induced liver fibrosis in vivo by inhibiting TGF-β1/Smad2/3, CUGBP1 signaling and activating IFN-γ/STAT1/Smad7 signaling." (PMID 35387552, 2022). "Furthermore, it has been reported that SM prevents immune-mediated liver injury and liver fibrosis through modulating the NF-κB and IFN-γ/STAT1 signaling pathways as well as enhancing NK cell activity." (PMID 31871483, 2019). "STAT1 has also been shown to be a negative regulator of hepatic fibrosis, where IFN-γ treatment of Stat1+/+ mice did not result in fibrosis while the same treatment of Stat1−/− mice resulted in increased hepatic fibrosis and accelerated TGF-β1/Smad signaling." (PMID 28716119, 2017). "Our results demonstrated that SCST could target HSP90AA1, PPARG, HSP90AB1, STAT1, etc., further regulating the PPARG signalling pathway that is closely related to liver fibrosis, and the flavonoids and phenylpropanoids of SCST are important ingredients against hepatic fibrosis." (PMID 33510287, 2021). "Although STAT1 and HSP90AA1 have no direct targets, SCST indirectly affects PPARG, STAT1 and HSP90AA1 to exert anti-fibrosis effects through XDH, which is also closely related to liver fibrosis." (PMID 33510287, 2021). "Specifically, enhanced STAT1 activation in hepatic non-parenchymal cells, particularly in HSCs, has been related to the inhibition of HSC proliferation, reduction in TGF-β signaling, and stimulation of NK cell killing of activated HSCs, all of which attenuate liver fibrosis." (PMID 39062027, 2024).
Obesity (45 papers, 2017 to 2026). Accumulation of substantial excess body fat. "STAT1 emerges as a pivotal player in the regulation of mitochondrial function, insulin sensitivity, and obesity-associated inflammation." (PMID 40423250, 2025). "Grohmann and others have shown that oxidative stress caused by obesity inhibits the activity of protein tyrosine phosphatase and leads to the activation of STAT1." (PMID 34944373, 2021). "Adipose tissue expansion and obesity are associated with the activation of STAT1 and NF-κB signalling, which may account for the increase in IRF7 expression during postnatal adipocyte development and in obesity." (PMID 36443525, 2022). "A recent study reported that the inactivation of negative regulators of the STAT1 signaling in obesity can contribute to the development of MASH and HCC." (PMID 39605886, 2024). "Microarray data also showed the influence of obesity on the upregulation of STAT1, which plays a major role in interferon signaling." (PMID 36428692, 2022). "Our findings reveal that microbiota disturbances, obesity, oral consumption of food additives, and deregulation of STAT1/6 signaling might be etiological components of CRC development." (PMID 36768437, 2023). "Grohmann and colleagues demonstrated that the oxidative hepatic environment in obesity restrained the STAT1 and STAT3 phosphatase TCPTP, which led to potentiate STAT1 and STAT3 signaling, and further increase the risk of developing NASH and HCC in the setting of nutritional excess." (PMID 37008925, 2023). "Moreover, the footprint of excess IFNγ is suggested by increased adipocyte STAT1 expression in obesity and following short-term HFD administration in lean subjects." (PMID 36153324, 2022). "Oxidative hepatic environment in obesity models of NAFLD has been associated with increased STAT-1 and STAT-3 signaling and inactivated STAT-1 and STAT-3 phosphatase T cell protein tyrosine phosphate (TCPTP), promoting hepatic T cell recruitment, NASH, fibrosis and HCC." (PMID 36544761, 2022). "On the other hand, monocytes from mothers with obesity (n = 3/time point) exhibited suppression of genes involved in interferon signaling (STAT1, GBP5, PSMB8) and response to reactive oxygen species (STRBP, HEBP2, TRAP1, TRPA1) (p value <0.001) with gestational age." (PMID 34195568, 2021). "Interestingly, levels of plasma regulatory factors (IL1RA, PDGF, CCL22) were significantly elevated, whereas those of IL-27, which activates monocytes via the STAT1 signaling pathway, were lower in plasma of mothers with obesity at T3." (PMID 34195568, 2021). "These key findings suggest that targeting STAT1 and STAT3 signaling could be a therapeutic target for treating the inflammatory phenotype associated with senescence in obesity-driven T2DM." (PMID 33672392, 2021). "Thus, our study identified a novel link between ACAT1 mediated FA metabolism and epigenetic modification on STAT1/2 that uncovers a regulatory role of lipid metabolism in innate immune signaling and opens novel avenues for interventions in human diseases such as obesity." (PMID 38410425, 2024). "A maternal HF diet somewhat offset the increase in Stat1 expression caused by an HF diet in the sons, which illustrates that the gene expression changes caused by maternal obesity are not always the same as those caused by an individual’s obesity." (PMID 29447215, 2018). "In more detail, the obesity-induced oxidative environment leads to the inactivation of the T cell protein tyrosine phosphatase (TCPTP), upregulating STAT1 and STAT3 signaling." (PMID 37834153, 2023). "In the context of obesity, the oxidative hepatic environment inactivates T cell protein tyrosine phosphatase (TCPTP), a negative regulator of STAT1 and STAT3, and increases STAT1 and STAT3 activity." (PMID 37361533, 2023). "For example, CREB3, STAT1, and STAT3 are important regulators of glucose and lipid metabolism in models of high-fat diet and obesity." (PMID 36389068, 2022).